ERRFI1 (ERBB receptor feedback inhibitor 1)
Diseases named in the same sentence as ERRFI1 in open-access papers (continued):
Sharing a sentence is not in itself a finding about the gene and the disease.
melanoma (4 papers, 2019 to 2025). A malignant, usually aggressive tumor composed of atypical, neoplastic melanocytes. "Downregulation of ERRFI1 with the help of siRNA increased the susceptibility of melanoma cells toward BRAF inhibition (BRAFi) and resensitized BRAFi-resistant melanoma cells to BRAFi." (PMID 41044875, 2025). "Errfi1-null mice exhibit skin hyperplasia and increased susceptibility to carcinogen-induced skin papilloma and melanoma." (PMID 34206547, 2021). "Here, we show that the expression of ERRFI1 was upregulated in melanoma and negatively correlated with the expression of melanocytic differentiation markers, such as MITF and TYR." (PMID 41044875, 2025). "It has been shown that ERRFI1 alters negatively invasion and migration processes in malignant melanoma." (PMID 30641895, 2019). "In our work, the EGFR level was not determined, so further investigations are needed to evaluate the validity of ERRFI1 as a prognostic marker in different subtypes of malignant melanoma." (PMID 30641895, 2019). "Furthermore, we show that miR-200c targeted the 3'UTR of ERRFI1 and reduced its expression, resulting in the resensitization of BRAFi-resistant melanoma cells to BRAFi." (PMID 41044875, 2025). "According to our study, antibodies against CD271, GLDC, and ERRFI1 could be used as a tool to predict prognosis of overall survival at stage IV disease of malignant melanoma." (PMID 30641895, 2019). "These are EGFR, ERRFI1, IL6, JAK2, PLXNC1, RGL3 which were found to be upregulated and CBL, CDC42, PIK3R3, STAT3, UBE2D2 and YWHAZ which were found to be downregulated; Melanoma has PLXNC1 as upregulated and TGFA as downregulated gene." (PMID 34764329, 2021). "Malignant melanoma patients with tumor samples with an IHC score > 8 for Anti-CD271, >8 for Anti-GLDC, and >9 for Anti-ERRFI1 are more likely to die early and therefore show a poorer prognosis after diagnosis stage IV in comparison with patients with smaller IHC scores for the described antibodies." (PMID 30641895, 2019).
hepatocellular carcinoma (3 papers, 2020 to 2022). A malignant tumor that arises from hepatocytes. "HNK activates ERBB receptor feedback inhibitor 1 gene (ERRFI1) expression, encoded by ERRFI1, leading to EGFR inhibition in hepatocellular carcinoma (HCC)." (PMID 35453652, 2022). "Additionally, ERRFI1 is deeply involved in various physiological and pathogenic events, such as lung development, endometrial epithelial cell proliferation, lung tumorigenesis, gliomagenesis, hepatocellular carcinoma, and neointimal hyperplasia in vascular smooth muscle cells." (PMID 31969149, 2020).
metastatic melanoma (3 papers, 2019 to 2025). A melanoma that has spread from its primary site to another anatomic site. "We previously demonstrated that the neural crest (NC)-associated gene ERRFI1 is highly expressed in metastatic melanoma and correlates with a bad prognosis." (PMID 41044875, 2025). "Our study results suggest that ERRFI1 could be a potential therapeutic target for the treatment of metastatic melanoma." (PMID 41044875, 2025). "Indeed, an upregulation of CD271, GLDC, and ERRFI1 in metastatic melanoma is in line with a bad prognosis." (PMID 30641895, 2019).
papillary thyroid cancer (3 papers, 2016 to 2024). "In contrast, decreased expression of ERRFI1 is associated with a more aggressive phenotype of papillary thyroid cancer with BRAF mutation." (PMID 34206547, 2021). "For instance, promoter methylation of ERRFI1 has been observed in 79% of human papillary thyroid cancer patient samples, leading to decreased gene expression." (PMID 39143382, 2024). "Reduced Gene 33 expression has been reported in 79% of specimens of papillary thyroid cancer patients, likely a result of methylation of the ERRFI1 promotor." (PMID 34206547, 2021).
psoriasis (3 papers, 2020 to 2021). An autoimmune condition characterized by red, well-delineated plaques with silvery scales that are usually on the extensor surfaces and scalp. "A recent integrated analysis of public genomic data revealed a potential association between ERRFI1 with the risk of psoriasis, a chronic inflammatory skin condition." (PMID 34206547, 2021). "An enhancer variant in the chromosome 1p36.23 region and within the enhancer of ERRFI1 is associated with increased susceptibility for psoriasis." (PMID 34206547, 2021). "In particular, we proposed a model for the genetic mechanism of psoriasis risk SNP rs417065 and functional variant rs72635708 via a long-range ERRFI1 enhancer in the 1p36.23 region." (PMID 31969149, 2020). "Thus, we concluded that ERRFI1 is a novel target gene for psoriasis risk SNPs and involved in the pathogenesis in hepatocytes and fibroblasts." (PMID 31969149, 2020). "Although the identified variants might be involved in psoriasis risk, we focused on rs72635708 and the ERRFI1 gene for further analyses for ease of interpretation of the association with psoriasis risk." (PMID 31969149, 2020). "The minor allele rs72635708 (rs72635708-C) might affect the ERRFI1 promoter activity, which results in unstable expression of ERRFI1, enhancing the risk of psoriasis via disruption of lipid metabolism and skin cell proliferation." (PMID 31969149, 2020). "However, the CHi-C data showed interactions (CHiCAGO score ≥ 5) between the psoriasis LD block and the promoter of ERBB receptor feedback inhibitor 1 (ERRFI1), an important regulator of keratinocyte proliferation and differentiation, in both unstimulated and stimulated HaCaT cells." (PMID 32366252, 2020). "Therefore, rs726365708 might be a useful genetic marker to detect ERRFI1 activity and the level of EGFR-TKI resistance, enabling personalized clinical application of EGFR-TKIs for patients with cancer or psoriasis." (PMID 31969149, 2020).
adenoma (2 papers, 2014 to 2019). A neoplasm arising from the epithelium. "Consistent with a driver role of this mutation, previously germline homozygous disruption of ERRFI1 in mice induces hyperplasia and adenoma formation in the epithelium and development of spontaneous adenocarcinomas of the lung, gallbladder and biliary tract." (PMID 24550739, 2014).
atherosclerosis (2 papers, 2023 to 2025). A disease characterized by the build-up of fatty material and calcium deposition in the arterial wall resulting in partial or complete occlusion of the arterial lumen. "For example, ERBB receptor feedback inhibitor 1 (ERRFI1114) was proposed as a potential biomarker for OSA and atherosclerosis." (PMID 41040075, 2025). "ERRFI1 can also act on EGFR expressed in intimal smooth muscle cells of human atherosclerotic plaques and plays a key role in the development of atherosclerosis." (PMID 37699925, 2023).
liver cancer (2 papers, 2021 to 2024). An epithelial or non-epithelial malignant neoplasm that arises from the liver. "Although little is known about the role of MIG6 in liver cancer, ERRFI1 deletion has been found in 13% of humans with HCC, in contrast to the extremely low incidence (around 1%) of EGFR mutations." (PMID 33806040, 2021).
lung adenocarcinoma (2 papers, 2018 to 2024). A carcinoma that arises from the lung and is characterized by the presence of malignant glandular epithelial cells. "Additional analysis showed that high ERRFI1 mRNA expression levels were associated with a worse OS in patients with lung adenocarcinoma." (PMID 39096122, 2024). "ERRFI1 mRNA expression levels were significantly elevated in the combined data for both lung adenocarcinoma (LUAD) and lung squamous cell carcinoma (LUSC) tissues (p = 0.006) as well as for LUAD tissues (p = 0.003), but not for LUSC tissues (p = 0.956)." (PMID 39096122, 2024). "As a proof of concept of the clinical relevance of this new mechanism of adaptive resistance, we report that a patient with a MET‐amplified lung adenocarcinoma displayed deregulation of the miR‐205/ERRFI1 axis in concomitance with onset of clinical resistance to anti‐MET therapy." (PMID 30021798, 2018).
Sepsis (2 papers, 2023). Sepsis is defined as life-threatening organ dysfunction caused by a dysregulated host response to infection. "miR-152-3p was shown to promote sepsis-induced rat AKI by targeting ERBB receptor feedback inhibitor 1 (ERRFI1), leading to an increase in STAT3 expression, resulting in promoting cell apoptosis and inflammation." (PMID 37761260, 2023). "Moreover, in sepsis-induced acute kidney injury, miR-152-3p was reported to aggravate apoptosis and inflammation by targeting ERRFI1.However, recent evidence shows that miR-152 has an antiapoptotic action in different models." (PMID 36445489, 2023).
thyroid cancer (2 papers, 2021 to 2024). "While most studies have focused on the role of ERRFI1 in cancer research, where it is thought of as a tumor suppressor gene due to its low expression levels in different cancer types like lung, breast, and thyroid cancer, limited research has been conducted on its role in aging." (PMID 38380598, 2024).
breast tumours (1 paper, 2007). "The RNA expression analysis of ERRFI1 showed a two-fold increase in unfavourable tumour compared to favourable, seemingly contradicting the results of another study that found ERRFI1 downregulation in breast tumours in patients with poor prognosis." (PMID 17940511, 2007).
cholangiocarcinoma (1 paper, 2021). A carcinoma that arises from the intrahepatic biliary tree (intrahepatic cholangiocarcinoma) or from the junction, or adjacent to the junction, of the right and left hepatic ducts (hilar cholangiocarcinoma). "As a key gene targeted AKT/EGFR signaling, ERRFI1 may be a binding target for some miRNAs and lncRNAs in various cancers, such as cholangiocarcinoma." (PMID 33789615, 2021).
diabetes (1 paper, 2019). "G allele of +808T/G polymorphism in ERRFI1 gene has no significant role in development and progression of diabetic nephropathy in diabetes patients while it is a risk allele for developing diabetes in Iranian population." (PMID 32351909, 2019).
diabetic nephropathy (1 paper, 2019). "This study aimed to investigate the role of +808T/G polymorphism (rs377349) in ERRFI1 gene in diabetic nephropathy." (PMID 32351909, 2019). "ERRFI1 gene which participates in various cellular pathways has been proposed as a candidate gene in diabetic nephropathy." (PMID 32351909, 2019).
endometriosis (1 paper, 2024). The growth of functional endometrial tissue in anatomic sites outside the uterine body. "Interestingly, endometriosis-associated gene dysregulation in early secretory phase matches dysregulation in the transgenic mouse endometrium in the present study in terms of affected gene-set, above all the progesterone-regulated genes (e.g. Errfi1, Bcl6, Cited2, Irs2, Tgfb2, Gpx3, Tk1)." (PMID 38346980, 2024).
Fulminant hepatic failure (1 paper, 2021). Hepatic failure refers to the inability of the liver to perform its normal synthetic and metabolic functions, which can result in coagulopathy and alteration in the mental status of a previously healthy individual. "Errfi1 is dramatically induced in the liver immediately after partial hepatectomy in rats and ERRFI1 is strongly induced in the liver of patients suffering fulminant hepatic failure." (PMID 34206547, 2021).
Hyperglycemia (1 paper, 2021). An increased concentration of glucose in the blood. "In contrast, mice with liver-specific knockout of Errfi1 exhibit hyperglycemia as a result of hepatic insulin resistance." (PMID 34206547, 2021). "Interestingly, another study showed that liver-specific knockout of Errfi1 in mice leads to fatty liver, fasting hyperglycemia, and hypercholesterolemia but lower body weight and higher insulin sensitivity." (PMID 34206547, 2021).
Hypertension (1 paper, 2014). The presence of chronic increased pressure in the systemic arterial system. "‘Unknown I’ contained a diverse set of key driver genes such as SGK1, SIK1 and SLC10A6 (sodium metabolism and hypertension), MT2A and TSC22D3 (glucocorticoid signaling), GADD45G, ERRFI1, GPRC5A, and EGFR (cell growth and apoptosis), and CEBPB, CEBPD, and KCNA5 (heart development and function)." (PMID 25033284, 2014).
Insulin resistance (1 paper, 2020). Increased resistance towards insulin, that is, diminished effectiveness of insulin in reducing blood glucose levels. "Errfi1 liver-specific knockout in mice altered expression of lipid and glucose metabolism-related genes, resulting in increased blood cholesterol and fasting glucose levels and leading to insulin resistance." (PMID 31969149, 2020).
ischemia (1 paper, 2020). A hypoperfusion of the BLOOD through an organ or tissue caused by a PATHOLOGIC CONSTRICTION or obstruction of its BLOOD VESSELS, or an absence of BLOOD CIRCULATION. "Interestingly, a previous study has shown that exosomes derived miR-126 possess the ability to regulate ERRFI1 to improve oxidative stress and apoptosis after the occurrence of ischemia and reperfusion injury." (PMID 33117083, 2020).
kidney cancer (1 paper, 2018). Primary or metastatic malignant neoplasm involving the kidney. "ERRFI1 (ErbB Receptor Feedback Inhibitor 1) – which encodes the protein MIG6 – is located within chromosome 1p36.1–3, a hotspot region frequently deleted in a broad range of human cancers, including breast, liver and kidney cancers." (PMID 29455648, 2018).
muscular atrophy (1 paper, 2019). The loss of muscle tissue due to inactivity or disease. "We also included ERRFI1, which encodes for a negative regulator of the RTK signalling, and the E3 ligase FBXO32/Mafbx/Atrogin1, involved in muscular atrophy." (PMID 31081251, 2019).
Nephropathy (1 paper, 2019). A nonspecific term referring to disease or damage of the kidneys. "ERRFI1 gene transcription is enhanced by stress-activated protein kinases (SAPKs) which can lead to hypertrophy and progression towards nephropathy." (PMID 32351909, 2019). "In nephropathy, SAPKs activate ERRFI1 transcription and activated ERRFI1 triggers the stability and expression of SAPKs." (PMID 32351909, 2019).
Obesity (1 paper, 2018). Accumulation of substantial excess body fat. "Surprisingly, we did not detect any major effect of injury and obesity on the expression levels of TNF or the associated genes Bcl3, Errfi1, Irak3, Myd88, and Thbs1 in our obese model." (PMID 29922174, 2018).
osteoarthritis (1 paper, 2021). A noninflammatory degenerative joint disease occurring chiefly in older persons, characterized by degeneration of the articular cartilage, hypertrophy of bone at the margins and changes in the synovial membrane. "Whole-body Errfi1 knockout mice, although born normal, develop degenerative joint disease resembling human osteoarthritis as a result of mesenchymal progenitor cell over-proliferation and die within 6 months of age." (PMID 34206547, 2021). "Interestingly, cartilage-specific overexpression of Errfi1 also accelerates cartilage degeneration, which leads to osteoarthritis in mice at an older age of 12–18 months." (PMID 34206547, 2021).
Parkinson disease (1 paper, 2017). A progressive degenerative disorder of the central nervous system characterized by loss of dopamine producing neurons in the substantia nigra and the presence of Lewy bodies in the substantia nigra and locus coeruleus. "Park7(DJ-1)/Errfi1 locus is involved in Parkinson’s disease." (PMID 29387450, 2017).
rectal cancer (1 paper, 2018). A primary or metastatic malignant neoplasm that affects the rectum. "The protein expression of ERRFI1 in three pairs of the induced rectal cancer cell lines was confirmed by Western Blot analysis." (PMID 29801473, 2018). "In this present study, the basal mRNA and protein level of ERRFI1 was up-regulated in the induced radio-resistant human rectal cancer cell lines." (PMID 29801473, 2018). "Among them, ERRFI1 and NDRG1 became final gene of interest as their mRNA and protein expression level was highly increased in radio-resistant rectal cancer cells." (PMID 29801473, 2018). "A microarray analysis indicated the RNA expression of five genes (NDRG1, ERRFI1, H19, MPZL3, and UCA1) was highly increased in radio-resistant rectal cancer cell lines." (PMID 29801473, 2018).
skin tumors (1 paper, 2021). "Indeed, whole-body ERRFI1 deletion in mice led to the development of rectal, gastric, gall bladder, bile duct, lung, and skin tumors." (PMID 33806040, 2021).